NPY (neuropeptide Y)
Diseases named in the same sentence as NPY in open-access papers (continued):
Sharing a sentence is not in itself a finding about the gene and the disease.
alcohol use disorder (8 papers, 2008 to 2025). "To date, no meta-analysis has been conducted to investigate the relationship between the NPY gene rs16139 polymorphism and the risk of alcohol use disorders." (PMID 34777047, 2021). "NPY and its receptors have been shown to be of importance in central regulation of events underlying, for example, affective disorders, drug/alcohol use disorders, and energy homeostasis." (PMID 28824541, 2017). "Hence, manipulating the NPY system appears to be a promising target for combating the neural alterations, alcohol use disorder related behaviors, and cognitive deficits caused by many drugs." (PMID 34777047, 2021). "In view of these promising results, more preclinical studies are needed in order to further evaluate the therapeutic potential of neuropeptide Y in the treatment of alcohol use disorder." (PMID 36263121, 2022). "Despite a breadth of studies demonstrating that NPY influences alcohol use disorder a few have suggested a link between cortical NPY signaling and alcohol use disorder." (PMID 35800635, 2022). "The roles of neuropeptide S (NPS) and neuropeptide Y (NPY) in alcohol use disorder are reported by Rodriguz and Covenas." (PMID 34466439, 2018). "The potential roles of NPY in the etiology and pathophysiology of mood and anxiety disorders, as well as alcohol use disorders, have been extensively studied." (PMID 28824541, 2017). "Neuropeptide Y and its derivates therefore seem to be a promising new therapeutic strategy for reducing binge-like alcohol consumption, preventing progression from harmful alcohol use towards alcohol use disorder, as well as for the treatment of alcohol use disorder." (PMID 36263121, 2022). "In conclusion, we suggest that modulation of NPY-ergic activity within the CNS, via ligands aimed at different receptor subtypes, may be attractive targets for treatment development for affective disorders, as well as for alcohol use disorders." (PMID 28824541, 2017). "In preliminary rodent studies, neuropeptide Y suppressed alcohol-induced inhibitory GABA release in central amygdala neurons and thus reduced the alcohol-reinforcement response in alcohol use disorder." (PMID 36263121, 2022). "These functions of NPY, in addition to the peptide’s regulation of disease states, suggest that modulation of the activity of the NPY system via receptor agonists/antagonists may be a putative treatment mechanism in affective disorders as well as alcohol use disorders." (PMID 28824541, 2017). "In the study period, the labels of the top ten clusters were: #0 NPY, #1 GLT-1, #2 acamprosate, #3 GABAA receptor subtypes, #4 EAAT2, #5 baclofen, #7 corticotropin releasing hormone receptor 1 (CRHR1), #8 alcohol use disorder, #9 C57BL/6, #10 COR659 (a GABAB positive allosteric modulator)." (PMID 36032235, 2022).
hepatocellular carcinoma (8 papers, 2013 to 2023). A malignant tumor that arises from hepatocytes. "NPY decreased PD-1+ T cells and PD-1 expression/cell in T cells of both healthy individuals and patients with hepatocellular carcinoma; the peptide augmented T cell proliferation and the eradication of hepatocellular carcinoma cells." (PMID 37373115, 2023). "By contrast, an increased Y5R expression was correlated with survival and tumor growth in hepatocellular carcinoma; NPY/Y5R are involved in tumor cell proliferation, migration, and invasion." (PMID 37373115, 2023). "Via NPY1R, NPY inhibits the growth of hepatocellular carcinomas by inactivating the mitogen-activated protein kinase signaling pathway." (PMID 29100314, 2017). "NPY also inhibited tumor cell growth and invasion in cholangiocarcinoma; both effects were counteracted with antibodies against NPY, and via Y1R, NPY blocked tumor cell growth in hepatocellular carcinoma." (PMID 37373115, 2023). "In an experimental animal model of hepatocellular carcinoma, the Ciji-Hua’ai-Baosheng II formula (a traditional Chinese medicine strategy targeting the adverse effects mediated by chemotherapy in cancer patients) increased serum NPY level and NPY expression in the hypothalamus." (PMID 37373115, 2023). "NPY, via Y1R, blocks tumor cell growth by inactivating the MAPK pathway in human hepatocellular carcinoma." (PMID 37373115, 2023). "NPY and Y2R, but not Y5R expressions, increased in hepatocytes placed close to the stromal–parenchymal interface in hepatocellular carcinoma." (PMID 37373115, 2023).
hyperlipidemia (8 papers, 2009 to 2024). "First, high levels of NPY could lead to hyperphagia, which has been reported to cause a variety of metabolic diseases, such as hyperlipidemia and T2DM." (PMID 32831640, 2020). "An NPY variant rare in most populations has been associated in Scandinavian populations with hyperlipidemia and carotid atherosclerosis, CAD in type 1 diabetics, and MI in hypertensive patients; however, the effects of this variant on NPY expression remain obscure." (PMID 19119412, 2009). "In rats, twelve weeks of HFD consumption induced hyperlipidemia by significantly increasing orexigenic NPY by 202% (P=0.0003) and concomitantly enhancing Y1 receptor expression by 172.3% (P<0.0001), as compared with the ND group." (PMID 38645495, 2024). "In the present study, HFD-induced hyperlipidemia was correlated with a significant increase in cortisol, insulin, NPY, and Y1 mRNA levels." (PMID 38645495, 2024). "In addition, it has been demonstrated that hyperlipidemia leads to increased NPY secretion in the central nervous system of the brain, which is also in agreement with our findings." (PMID 39770951, 2024). "Therefore, serum NPY synthesis can be elevated in obese participants with hyperlipidemia." (PMID 32831640, 2020). "Proopiomelanocortin (POMC), an appetite-inhibiting neuropeptide, is decreased by increased levels of appetite-stimulating neuropeptides such as neuropeptide Y (NPY) and agouti-related peptide (AgRP), which reduces energy expenditure, increases food intake, weight gain, and hyperlipidemia." (PMID 37425327, 2023).
Seizure (8 papers, 2011 to 2025). A seizure is an intermittent abnormality of nervous system physiology characterized by a transient occurrence of signs and/or symptoms due to abnormal excessive or synchronous neuronal activity in the brain. "Experimental studies involving models of epileptic seizures have highlighted intriguing findings regarding NPY’s expression." (PMID 40217521, 2023). "Further support for this notion is provided by investigations showcasing diminished occurrences of spontaneous epileptic seizures and the prevention of epileptogenesis through NPY gene therapy in experimental animal models." (PMID 40217521, 2023). "Given the high levels of colocalization of phogrin with NPY, it would be interesting to address the potential implication of this protein in regulating NPY levels and its relationship to epileptic seizures." (PMID 27630542, 2016). "Epileptic seizures result in pronounced over-expression of neuropeptide Y (NPY)." (PMID 36311021, 2022).
status epilepticus (8 papers, 2011 to 2023). Status epilepticus is defined as a continuous seizure lasting more than 30 min, or two or more seizures without full recovery of consciousness between any of them. "Early anticonvulsant treatment with MK-801 or thiopental after the initial KA-induced status epilepticus prevented the subsequent increases in NPY and somatostatin levels." (PMID 36311021, 2022). "Measuring NPY levels in brain areas after a KA-induced status epilepticus revealed an initial drop in the levels of the peptide due to its extensive release and degradation during and after the acute seizures." (PMID 36311021, 2022). "Similarly, combined Y5 and NPY overexpression resulted in a synergistic inhibitory effect on kainic acid (KA)-induced acute status epilepticus (SE) seizures." (PMID 31660420, 2019). "Additionally, NPY knockout mice, compared to wild-type, exhibited more frequent EEG seizures that were longer in duration and progressed to status epilepticus and death within an hour after kainic acid administration, and further, NPY pretreatment prevented the mortality." (PMID 29377906, 2018). "We found that the AAV1 serotype with a gene sequence of NPY-IRES-Y2 (AAV1-NPY/Y2) had a significant pharmacodynamic effect by reducing time spent in motor seizures and increasing the latency to status epilepticus (SE) induced by systemic KA in male Wistar rats." (PMID 37029201, 2023).
anorexia nervosa (7 papers, 2011 to 2023). A disorder most often seen in adolescent females characterized by a refusal to maintain a minimally normal body weight, an intense fear of gaining weight, a disturbance in body image, and, in postmenarcheal females, the development of amenorrhea. "Adolescent mice with anorexia nervosa display cognitive decline, and central inhibition of agouti-related peptide (AgRP) and neuropeptide Y (NPY) reverses the cognitive decline." (PMID 37168929, 2023). "Status of anorexia nervosa was found to be positively correlated with plasma levels of ghrelin, obestatin, NPY and PYY and negatively correlated with BMI, percent of body fat and weight." (PMID 22681985, 2012). "It has been reported that NPY can attenuate specific behavior when the organism is stressed and anti-stress effects of NPY are relevant to psychiatric conditions such as anorexia nervosa (AN) and BN." (PMID 22093818, 2011). "As status of anorexia nervosa was found to be positively correlated with plasma levels of ghrelin, obestatin, NPY and PYY, we suppose that all these hormones are included in pathology of eating disorder and their levels are changed probably as a consequence of eating disorder." (PMID 22681985, 2012). "The present study investigated plasma levels of gut-brain axis peptides ghrelin, obestatin, NPY and PYY after consumption of a high-carbohydrate (HC) and high-protein (HP) breakfast in patients with anorexia nervosa, bulimia nervosa and in healthy controls." (PMID 22681985, 2012).
bipolar disorder (7 papers, 2008 to 2022). A disorder of the brain that causes unusual shifts in mood, energy, activity levels and the ability to carry out day-to-day tasks. "The present study identified a significant association between NPY-LA and DGKH, a gene that has previously been reported in bipolar disorders." (PMID 35627254, 2022). "Male rats treated with Lithium exhibited increased NPY-like immunoreactivity in the frontal cortex, suggesting that NPY may be involved in the response to treatments to MDD and bipolar disorder." (PMID 33192369, 2020).
breast tumors (7 papers, 2011 to 2025). "In summary, this study suggests the potential of heterobivalent radioligand [99mTc]-HYNIC-cRDGfk-NPY to target breast tumors by targeting more than one biomarker as an agent for SPECT imaging." (PMID 39458969, 2024). "This article details the development and preclinical evaluation, both in vitro and in vivo, of a novel heterodimer peptide dual-receptor-targeting probe, [99mTc]HYNIC-cRGDfk-NPY, designed for imaging breast tumors." (PMID 39458969, 2024). "For such a multireceptor approach, good candidate tumors seem to be breast tumors targeted with NPY and bombesin analogs." (PMID 22214201, 2011). "Moreover, NPY-loaded immune-stimulating complexes decreased breast tumor cell growth by promoting apoptosis." (PMID 37373115, 2023). "The 18F-glycopeptide [Pra4([18F]FGlc),F7,P34]NPY can be considered as a lead peptide for the design of improved glycopeptide tracers with shorter amino acid sequences for imaging of Y1R-positve breast tumors by PET." (PMID 34832957, 2021).
Cachexia (7 papers, 2010 to 2024). Severe weight loss, wasting of muscle, loss of appetite, and general debility related to a chronic disease. "A primary mechanism in cancer-depended cachexia occurs through dysregulation of the hypothalamic axes related to energy uptake such as neuropeptide Y (NPY) and proopiomelanocortin (POMC)/cocaine pathways." (PMID 32466362, 2020). "Zinc increases the expression of NPY and orexin m-RNA in experimental animals and plays a role in limiting the progression of cachexia and sarcopenia." (PMID 30823566, 2019). "However, NPY mRNA expression in the hypothalamus increases in animal models of chronic inflammatory diseases characterized by cachexia, such as cancer cachexia and arthritis." (PMID 34899611, 2021). "Independently of feeding status, AA induced cachexia, in which modulation of mRNA expressions for appetite-regulating neuropeptides (NPY, AgRP, POMC, CART) in the arcuate nucleus (ARC) does not play a primary role." (PMID 20953376, 2010). "Therefore the upregulation of NPY/AgRP mRNA expression in the ARC is not surprising in arthritic rats, and reflects physiological response in cachexia." (PMID 20953376, 2010).
chronic kidney disease (7 papers, 2009 to 2023). Impairment of the renal function secondary to chronic kidney damage persisting for three or more months. "Previous studies in patients with end stage renal disease indicated that elevated NPY is independently associated with LV concentric hypertrophy and systolic dysfunction." (PMID 27855650, 2016). "Numerous humoral factors, in particular angiotensin II but also NPY, contribute to podocyte activation in chronic renal failure but also the mechanical environment changes." (PMID 24244677, 2013). "In addition, neuropeptide Y (NPY), which is normally produced in peripheral nerve endings, accumulates in the circulation of chronic kidney disease and ESKD patients." (PMID 34917635, 2021).
cognitive decline (7 papers, 2017 to 2026). "Impaired awareness of cognitive decline may lead to neglect of dietary needs, while malnutrition-induced neurobiological changes (e.g., altered neuropeptide Y levels) may exacerbate SCD symptoms." (PMID 41211392, 2025). "This Aβ-mediated inhibition of hypothalamic neuropeptide Y (NPY) neurons may induce a catabolic state with low leptin, contributing to further neurodegeneration and cognitive decline." (PMID 41516046, 2025). "Taken together, those changes in mRNA expression as well as POMC and NPY-expressing neuronal alterations suggest that exercise training is sufficient to change outcomes related to hypothalamic function in the 3xtg-AD model at a critical point before the development of cognitive decline." (PMID 29293568, 2018). "Preclinical AD models show that neuroprotective neuropeptides, such as neuropeptide Y (NPY), vasoactive intestinal peptide (VIP), and pituitary adenylate cyclase-activating peptide (PACAP), exert neuroprotective effects, enhance memory, and attenuate cognitive decline." (PMID 41977389, 2026).
malnutrition (7 papers, 2017 to 2025). Inadequate nutrition resulting from poor diet, malabsorption, or abnormal nutrient distribution. "The expression of NPY is dynamically regulated by the body’s energy status: under conditions of optimal nutrition, the amount of NPY in nerve cells decreases, while starvation and/or malnutrition elevate its secretion." (PMID 40806524, 2025). "Indeed, in a situation of negative energy balance, such as the malnutrition occurring in the majority of ALS patients, the expression of NPY would be normally increased." (PMID 36460700, 2022). "Thus, in a situation of negative energy balance, such as the malnutrition observed in ALS, the expression of NPY and AgRP is normally increased and POMC expression decreased." (PMID 34638645, 2021).
myocardial ischemia (7 papers, 2018 to 2024). A disorder of cardiac function caused by insufficient blood flow to the muscle tissue of the heart. "Clinical studies have confirmed that elevated plasma NPY levels are associated with myocardial ischemia and infarction, and NPY levels can be used to inform disease severity and prognosis." (PMID 34344469, 2021). "Evidence suggests that an excited sympathetic nervous system induced by an acute coronary heart attack, can promote NPY release, thereby causing coronary artery spasm and aggravating further myocardial ischemia." (PMID 33708805, 2021). "NPY significantly increases infarct area in relation to the area at risk during myocardial ischemia–reperfusion (I/R) injury, which is blunted by NPY1R antagonist BIBO3304." (PMID 31708788, 2019). "Studies have shown that intracoronary injection of NPY in patients with angina pectoris may cause myocardial ischemia, which manifests as chest pain and an abnormal electrocardiogram result." (PMID 34344469, 2021). "NPY has previously been shown to induce myocardial ischemia, demonstrable through ECG ST‐T wave changes, reduction of intramyocardial pH, and LVEF in dogs." (PMID 35766271, 2022). "In this study, we evaluated for the first time the role of NPY-KO in cardiac ischemia for 3 days after ligation of left coronary artery induction in rats and 4 h after treatment with H2O2 and 12 h after treatment with hypoxia in cardiomyocytes." (PMID 31708788, 2019). "Collectively, deletion of NPY reduced myocardial ischemia, improved cardiac function, and inhibited cardiomyocyte apoptosis by NPY type 1 receptor–miR-499–FoxO4 axis, which provides a new treatment for MI." (PMID 31708788, 2019). "The vasoconstrictive effects of NPY in the coronary arteries results in ST-T wave alterations and reduction in intra-myocardial pH and left ventricle ejection fraction, inducing myocardial ischemia in dogs." (PMID 30283345, 2018). "Despite these potential beneficial effects, however, other studies have suggested detrimental actions of NPY in relation to myocardial ischemia." (PMID 30283345, 2018).